PIN1 (peptidylprolyl cis/trans isomerase, NIMA-interacting 1)
Diseases named in the same sentence as PIN1 in open-access papers (continued):
Sharing a sentence is not in itself a finding about the gene and the disease.
Hyperglycemia (8 papers, 2016 to 2024). An increased concentration of glucose in the blood. "The role and underlying mechanism of the Pin1/BRD4 axis in hyperglycemia-induced proliferation and migration of GC cells were analyzed in vivo and in vitro." (PMID 35461311, 2022). "This study explored hyperglycemia-induced proliferation and migration of GC cells, and the underlying involvement of the Pin1/BRD4 signal pathway, both in vitro and in vivo." (PMID 35461311, 2022). "In summary, we revealed the critical role of Pin1/BRD4 axis in the association between hyperglycemia and GC." (PMID 35461311, 2022). "Experiments in KO mice, primary human endothelial cells and peripheral blood monocytes (PBMCs) of T2D patients demonstrated that hyperglycemia caused Pin1 upregulation and the latter, in turn, mediated vascular-damage occurring in diabetic patients." (PMID 30096758, 2018). "Hyperglycemia was associated with reduced methylation of the Pin1 gene promoter, and that is another finding commonly observed also in patients with AD." (PMID 30096758, 2018). "Thus, our results imply that even if hyperglycemia-induced upregulation of Pin1 might cause similar stresses to the brain vasculature, these do not induce significant BBB disruption." (PMID 30498224, 2018). "In vivo studies indicated that hyperglycemia promotes tumor growth and lung metastasis by inducing Pin1 and BRD4 expression." (PMID 35461311, 2022). "In summary, hyperglycemia-induced Pin1/BRD4 axis promoted gastric tumorigenicity and tumor metastasis by facilitating NAP1L1 and repressing P21 in vivo." (PMID 35461311, 2022). "Our previous studies have indicated that Pin1 promotes inflammatory responses and oxidative stress, and participates in hyperglycemia-induced inflammation." (PMID 35461311, 2022). "Pin1 has previously been reported to be upregulated in an in vitro model of hyperglycemia and in the aorta of streptozotocin-induced diabetic mice, resulting in mitochondrial oxidative stress, vascular relaxation dysfunction and vascular inflammation." (PMID 30498224, 2018). "In fact, interestingly, recent studies have revealed that Pin1 expression is increased in the aortas of mice with streptozotocin (STZ)-induced hyperglycemia as well as in the arterial walls of those treated with serum from diabetic mice." (PMID 27618008, 2016). "Inhibition of Pin1 or BRD4 significantly inhibited pulmonary metastasis induced by hyperglycemia." (PMID 35461311, 2022). "In particular, methylation of Pin1 promoter, which typically represses gene transcription, was substantially decreased during hyperglycemia, suggesting that this epigenetic modification may contribute to Pin1 upregulation." (PMID 34943794, 2021). "Moreover, in STZ-treated mice, Pin1 overexpression in the liver improves hyperglycemia and suppresses increases in PEPCK and G6Pase." (PMID 27618008, 2016). "Thus, Pin1/BRD4 plays an important role in hyperglycemia-promoted tumor growth." (PMID 35461311, 2022). "However, whether hyperglycemia promotes high Pin1 expression in tumor tissues, leading to increased BRD4 expression and tumor cell proliferation, remains unclear." (PMID 35461311, 2022). "Moreover, during hyperglycemia, Pin1 has been shown to interact with eNOS at Ser116 phosphorylation site, thereby promoting eNOS interaction with caveolin-1, an important repressor of eNOS catalytic activity in the endothelium and subsequently reducing NO availability." (PMID 34943794, 2021). "Therefore, a possible interaction between Pin1 and NADPH may also exist in HUVEC under hyperglycemia condition, which needs our further research." (PMID 29849865, 2018).
Insulin resistance (8 papers, 2013 to 2024). Increased resistance towards insulin, that is, diminished effectiveness of insulin in reducing blood glucose levels. "Consistently, further in vivo loss-of-function experiments demonstrated that Pin1 knockout had an inhibitory effect against hepatic steatosis, inflammation, insulin resistance, and fibrosis in NAFLD progression." (PMID 38892011, 2024). "As revealed by the OGTT and ITT assays, glucose intolerance and insulin resistance were enhanced in Pin1-KO mice relative to Pin1-WT mice." (PMID 38892011, 2024). "Conversely, it enhanced cell viability and anti-apoptotic signals and reduced ROS levels in Pin1 KD clones when exposed to MG, a compound that induces insulin resistance." (PMID 31614723, 2019). "Consequently, HFD feeding is considered to cancel the positive effect of Pin1 on IRS-1, instead causing insulin resistance." (PMID 27618008, 2016). "The results indicate that Pin1 knockdown significantly alleviated hepatic steatosis, fibrosis and inflammation in MCD-induced NAFLD mice, improved glucose tolerance and alleviated insulin resistance in mice." (PMID 38892011, 2024). "Pin1 also positively regulates insulin-induced phosphorylation of IRS-1: Pin1 deletion inactivates IRS-1, thus leading to insulin resistance." (PMID 33537091, 2021).
Stroke (8 papers, 2014 to 2025). Sudden impairment of blood flow to a part of the brain due to occlusion or rupture of an artery to the brain. "Pin1-deficiency has been found to prevent stroke-induced brain damage and neurological deficits in Pin1−/− mice." (PMID 33083964, 2021). "Similar to AD, TBI/CTE, and stroke/VaD, our group demonstrated a preE-associated Pin1 inactivation by cysteine-113 (Cys113) oxidation, and Ser71 phosphorylation by death associated protein kinase 1 (DAPK1), and concomitant induction and cytoplasmic sequestration of cis P-tau and protein aggregation." (PMID 39857613, 2024). "In view of that there could be a pathogenic synergy between the two disease processes, stroke and AD might effectively share common risk factors: in this scenery the role of Pin1 in HIF-1α isomerization and degradation may outcome as central mechanism in vascular damages vs. AD and vice versa." (PMID 24478626, 2014). "As seen in AD, TBI, or stroke, Pin1 is inhibited by phosphorylation, oxidation, cytoplasmic sequestration, or mutations." (PMID 39857613, 2024). "Paradoxically, Pin1-mediated ubiquitination seems to play context-dependent, contrasting roles that are still not fully understood—for instance, promoting cell death in stroke, but binding protectively in spinal cord injury." (PMID 38727267, 2024). "Beyond classical neurodegenerative diseases, Pin1-mediated ubiquitination has emerged as a regulator of adjacent neurological disorders, such as epilepsy, stroke, spinal cord injury, retinal disease, and even physiological aging, although its role is much less defined." (PMID 38727267, 2024). "Notably in AD, TBI/CTE and stroke/VaD, Pin1 is also catalytically inactivated by Cys113 oxidization or Ser71 phosphorylation by DAPK140,41,68." (PMID 37669931, 2023). "The current study reveals a novel therapeutic mechanism by which BM-MSC-derived migrasomes alleviate poststroke immunosuppression through targeted delivery of the Pin1 protein to TEC, thereby reversing stroke-induced thymic atrophy and restoring peripheral immune homeostasis." (PMID 41241718, 2025). "It has been shown that DAPK1 activation triggers aberrant tau phosphorylation in AD and stroke 12, 16, while whether DAPK1 and Pin1 also participate in Aβ species-induced tau dysregulation remains to be determined." (PMID 35002518, 2022).
asthma (7 papers, 2008 to 2021). "The regulation of Rho GTPases and their signaling illustrates and extends the vital and pleiotropic role for Pin1 in Eos function and, by extension, the pathophysiology of asthma and possibly other eosinophilic pathologies." (PMID 33494375, 2021). "Of specific relevance to asthma are studies showing that PIN1 is abnormally activated in eosinophils in asthmatic airways and that PIN1 increases key cytokine production necessary for eosinophils survival and activation by stabilizing their mRNA half-life." (PMID 29686383, 2018). "PIN1 protein expression did not seem to change upon Derp1 treatment, but we did observe a decrease in pS71 phosphorylation, consistent with the previous findings that PIN1 catalytic activity is elevated in the airway of human asthma patients." (PMID 29686383, 2018). "In animal models of asthma, systemic delivery of Pin1 inhibitors prevented airway inflammation by blocking the expression of eosinophil survival cytokines (GM-CSF and IL-5)." (PMID 25874604, 2015). "Conversely, Pin1 blockade prevented GM-CSF mRNA stabilization or cytokine secretion, and attenuated allergic inflammation and airway fibrosis in the rodent models of asthma." (PMID 25874604, 2015). "Recent studies have shown that Pin1 regulates cytokine gene expression and immune responses in several disorders (asthma, organ rejection, anti-viral immunity)." (PMID 25874604, 2015). "The prolyl cis-trans isomerase PIN1 is known to induce cytokines for eosinophil survival and activation by stabilizing cytokines mRNAs, but the function of PIN1 in upstream signaling pathways in asthma is unknown." (PMID 29686383, 2018). "Thus, pharmacologic modulation of Pin1 activity with small molecule inhibitors may provide a novel approach to eosinophilic diseases, such as asthma." (PMID 28971096, 2017). "Pin1 has been implicated in control of mRNA stability and turnover of the cytokine GM-CSF, Pth, and TGFβ mRNAs, all of which have AU-rich cis-elements (ARE) in their 3' untranslated regions (3' UTRs) and play important roles in control of the immune response in inflammation and asthma." (PMID 25992900, 2015). "In vivo Pin1 blockade significantly reduced pulmonary EOS counts, GM-CSF production, and cell viability in rat models of asthma." (PMID 28971096, 2017). "Pin1 was required for IL-5R-mediated survival signaling and Epstein-Barr virus-induced receptor 2 (EBI2)-induced transmigration of human blood Eos, suggesting a role for Pin1 in both the entry and enhanced pulmonary survival of Eos during asthma exacerbations." (PMID 33494375, 2021). "Since TSLP expression is blocked by a PIN1 inhibitor after challenging lung with allerges and the 3'-untranslated region of TSLP mRNA contain an AUF1 binding site, PIN1 is likely to be a modulator of TSLP expression in asthma at the posttranscriptional level." (PMID 18724870, 2008).
Huntington disease (7 papers, 2017 to 2024). Huntington disease (HD) is a rare neurodegenerative disorder of the central nervous system characterized by unwanted choreatic movements, behavioral and psychiatric disturbances and dementia. "Besides AD and PD, Pin1 has also been implicated in other neurodegenerative diseases like Huntington’s disease." (PMID 36111342, 2022). "Pin1 was reported to contribute also to the neurodegeneration seen in a mouse model of Huntington’s disease." (PMID 30096758, 2018). "Therefore, inhibition of Pin1 might represent a therapeutic target for the treatment of Huntington’s disease." (PMID 30096758, 2018). "In addition, the Pin1 modulation of proteins central to other neurodegenerative diseases, such as Parkinson’s Disease (PD) and Huntington’s Disease (HD), is an emerging area of research that should not be neglected." (PMID 38727267, 2024).
lymph node metastasis (7 papers, 2016 to 2023). "Pin1 overexpression in human LSILs is related to poor outcome and is associated with lymph node metastasis in CC patients." (PMID 32010480, 2020). "We concluded that Pin1 expression was positively associated with lymph node metastasis (P = 0.039) and Ki67 (P=0.014) but was not correlated with patient age (P = 0.724), tumour size (P = 0.927) and P16 (P=NA)." (PMID 32010480, 2020). "In the present study, Pin1 upregulation was suggested to be associated with advanced stage in PTC but not with other clinicopathological characteristics (age, gender, family history, muscle invasion, diameter of cancer, and lymph node metastasis)." (PMID 27029791, 2016). "According to the results, we showed that Pin1 upregulation was associated with advanced stage in PTC, but not with other clinicopathological characteristics (age, gender, family history, muscle invasion, diameter of cancer, and lymph node metastasis)." (PMID 27029791, 2016). "We further analyzed the expression of PIN1, YAP, and TAZ with the age, sex, place of onset, clinical staging, lymph node metastasis and other clinical pathological parameters of patients with OS, and the results were not significantly correlated due to the small number of samples we had." (PMID 37006999, 2023). "The remaining data showed that TPL2 expression was not correlated with lymph node metastasis, patient age, and tumor size, and Pin1 expression was also not correlated with the other clinicopathological parameters." (PMID 37833434, 2023). "The proportion of Pin1 detected in SCC cases with or without lymph node metastasis was 100 % and 54.5 %, respectively." (PMID 32010480, 2020).
neuroblastoma (7 papers, 2017 to 2025). Neuroblastoma (NB) is the most common solid, extracranial childhood tumor. "To test this hypothesis, we co-transfected GFP-tagged zebrafish Pin1 and HA-tagged Nrd were transiently co-transfected into neuroblastoma SH-SY5Y cells." (PMID 37791075, 2023). "Other oxidative modification sites in Pin1 have been identified at Met130 and Met146 in human neuroblastoma SH-SY5Y cells stably expressing Pin1, indicating that Pin1 might have multiple oxidation sites through which its function is regulated." (PMID 32195254, 2020). "In agreement with similar reports we observed that Pin1 accumulated in the nucleus of the cell lines analyzed, including neuroblastoma cells (SH-SY5Y, Neuro-2a), both in proliferation conditions and when differentiation was induced by treatment with all-trans retinoic acid." (PMID 28426725, 2017). "In an in vitro system of human neuroblastoma cell line, SH-SY5Y, we silenced the expression of Pin1 gene by RNA interference technique." (PMID 31614723, 2019). "Sulfopin is highly selective for Pin1, inhibits Pin1 in multiple cell lines, including MDA-MB-231 and HCT116, reduces tumor progression and tumor volume, and confers a significant survival benefit in a dose-dependent manner in a murine model of neuroblastoma." (PMID 38745861, 2024).
esophageal squamous cell carcinoma (6 papers, 2014 to 2024). Esophageal squamous cell carcinoma (ESCC) is a type of esophageal carcinoma (EC) that can affect any part of the esophagus, but is usually located in the upper or middle third. "In esophageal squamous cell carcinoma (ESCC), increased Pin1 expression is associated with worse outcome of ESCC patients." (PMID 32258027, 2020). "In this study, we investigated the involvement of Pin1 in tumor progression and in the prognosis of human esophageal squamous cell carcinoma (ESCC)." (PMID 25160749, 2014). "MiRNA-370 is downregulated in esophageal squamous cell carcinoma (ESCC) tissues and cells, and the downregulation of miR-370 in ESCC affects the proliferation of cancer cells through PIN1 upregulation." (PMID 32742452, 2020).
osteosarcoma (6 papers, 2014 to 2023). A usually aggressive malignant bone-forming mesenchymal neoplasm, predominantly affecting adolescents and young adults. "To confirm this interaction in mammalian cells, we transiently overexpressed HA‐tagged TAp63γ (HA‐TAp63γ), along with wild‐type Pin1 or its W34A mutant, in human osteosarcoma cell Saos‐2, and performed a co‐immunoprecipitation (CoIP) assay." (PMID 33548094, 2021). "In osteosarcoma, PIN1 overexpression using adenovirus significantly stimulates MG-63 and U2-OS cell proliferation." (PMID 32258027, 2020). "To further substantiate our findings, we generated PIN1 knockout (KO) U2OS human osteosarcoma cell lines by CRISPR-Cas9." (PMID 30789902, 2019). "Also, PIN1 inhibitor, juglone reduces cell proliferation in osteosarcoma cells." (PMID 32258027, 2020). "To verify this point, we adopted an siRNA-based approach to down-regulate endogenous Pin1 expression in the U2OS human osteosarcoma cell line, which does not express p63 endogenously." (PMID 24569166, 2014).
pancreatic ductal adenocarcinoma (6 papers, 2020 to 2024). An infiltrating adenocarcinoma that arises from the epithelial cells of the pancreas. "BJP-06-005-3 promotes Pin1 degradation, leading to a downstream suppression of Pin1-mediated Myc-Ras signaling pathways and reduced cell viability in pancreatic ductal adenocarcinoma." (PMID 37508437, 2023). "In pancreatic cancer, PIN1 was highly expressed in pancreatic ductal adenocarcinoma (PDAC) tissues and significantly correlated with the worst outcomes in patients." (PMID 32258027, 2020).
type 2 diabetes (6 papers, 2013 to 2023). "Dysfunctional expression of Pin1 causes deregulation of Pin1 substrates, a phenomenon that is associated with the onset of neurodegenerative and metabolic disorders including type 2 diabetes (T2D)." (PMID 31614723, 2019). "Deregulation of Pin1 substrates has been implied in the onset of various diseases, i.e., cancer, neurodegenerative disorders and metabolic syndromes including type 2 diabetes (T2D)." (PMID 30096758, 2018).